VCAN (versican)
Diseases named in the same sentence as VCAN in open-access papers (continued):
Sharing a sentence is not in itself a finding about the gene and the disease.
ovarian carcinoma (continued). "The cleavage of proteoglycans like aggrecan and versican by a disintegrin and metalloproteinase with thrombospondin motifs (ADAMTS) in epithelial ovarian cancer has been demonstrated and is considered of prognostic value." (PMID 32351878, 2020). "CSGP/VCAN was identified exclusively in EIC, was seen to have increased expression in COCC compared to other ovarian cancer cell types and had increased expression in SEC compared to healthy control tissue." (PMID 33384952, 2020). "Among these molecules, several have been shown to be relevant to ovarian cancer and proposed as biomarkers, including NID-2 and VCAN." (PMID 33019700, 2020). "Under TGF‐β stimulation, CAFs release high amount of versican, along with MMP‐9, resulting in increased aggressiveness of ovarian cancer." (PMID 28926101, 2018). "Examples include VCAN, VIM and IL32, mediators of cell motility and invasion when upregulated in ovarian cancers, HNSCCs and metastatic CRCs, respectively." (PMID 29228717, 2017). "Versican treatment can induce ovarian cancer cell invasion through an ECM barrier, and suggest that formation of a CD44/hyaluronan/versican macromolecular complex promotes the motility and invasion of ovarian cancer cells." (PMID 26515726, 2015). "The peritumoral stroma surrounding ovarian cancer cells is enriched in HA, versican and CD44 all of which can promote ovarian cancer metastatic behavior." (PMID 21541039, 2011). "Altered expression of several ECM molecules including versican, hyaluronan (HA) and CD44 have been described in ovarian cancer and impact on ovarian cancer outcome." (PMID 21541039, 2011). "This review focuses on versican, HA, and CD44 and their potential as therapeutic targets for ovarian cancer." (PMID 21541039, 2011). "Overall the combined data supports a role for versican together with HA and CD44 in a number of the key steps needed for ovarian cancer metastasis." (PMID 21541039, 2011). "ECM molecules including versican and hyaluronan (HA) which interacts with the HA receptor, CD44, have been shown to play critical roles in ovarian cancer metastasis." (PMID 21541039, 2011). "For example, many TGF-β signaling-related genes derived from CAFs play important roles in the crosstalk between fibroblasts and ovarian cancer, including periostin (POSTN), collagen type XI alpha 1 (COL11A1), collagen triple helix repeat containing-1 (CTHRC1), and versican (VCAN)." (PMID 35681617, 2022). "At the molecular level, we evaluated basal expression levels of the HA axis in a panel of ovarian cancer cell lines and compared control ovarian cancer cells and HAS2 knockdown cells regarding gene expression of HAS1-3 and HYAL2-3, CD44, RHAMM and versican by qPCR." (PMID 35767191, 2022). "However, VCAN and SDC3 transcripts were elevated in the blood of ovarian cancer patients and showed a considerable trend toward significance (P-values: VCAN = 0.052, SDC3 = 0.055)." (PMID 31336942, 2019). "Two genes (VCAN, MSH6) are common in endometrial, breast and ovarian cancers." (PMID 31205821, 2019). "For instance, VCAN and POSTN were demonstrated in vitro to be involved in ovarian cancer invasion induced by TGF-β signaling, and COL11A1 was shown to increase continuously during ovarian cancer progression and to be highly overexpressed in recurrent metastases." (PMID 27843486, 2016). "Moreover, dependence of CD44 on versican, a large HA-binding proteoglycan, has been shown in ovarian cancer where HA and versican form a pericellular matrix around CD44-expressing ovarian cancer cells that further promotes their motility and invasion in vitro." (PMID 26569327, 2015). "The ability of GM6001 and catechin gallate esters to inhibit versican cleavage and versican-induced motility and metastasis of ovarian cancer cells has not been investigated yet." (PMID 21541039, 2011).
ovarian carcinoma (continued). "Because miRNA3652 is downregulated in ovarian cancer cells, several signalling cascades, including the WNT—catenin signalling route, the MRTF-SRF pathway, and the Hedgehog signalling system, are stimulated, leading to the overexpression of the GL2, SRF, and VCAN genes." (PMID 37845675, 2023). "Finally, in ovarian cancer, versican expression does not appear to have prognostic significance, despite the finding that high stromal staining is related to poor disease-free survival." (PMID 23082892, 2012).
prostate carcinoma (31 papers, 2009 to 2025). A carcinoma that arises from epithelial cells of the prostate gland. "VCAN has been associated with the metastasis potential of malignant cells in prostate cancer and GCTs." (PMID 38791985, 2024). "Other studies have shown that increased VCAN is correlated with elevated prostate-specific antigen levels and poorer prognosis in prostate cancer, including an increased risk of metastasis following radical prostatectomy." (PMID 32354091, 2020). "VCAN expression is known to be up-regulated during prostate cancer progression and is linked to poor prognosis." (PMID 32354091, 2020). "It is slightly controversial with the published data on elevated levels of versican protein in prostate cancer, associated with disease progression in early-stage prostate cancer." (PMID 23691363, 2013). "VCAN was associated with the progression of prostate cancer." (PMID 30970615, 2019). "Taken together, the cited articles suggest a possible role of VCAN in prostate cancer biology, especially in promotion of tumor cell motility and invasion." (PMID 41470114, 2025). "The role of versican (VCAN) in prostate cancer biology is recognized in early studies and has already been known for a while." (PMID 41470114, 2025). "In prostate cancer, PGs have been shown to be involved in many steps of its progression; the most prominent examples include the seemingly tumor-promoting roles of versican, perlecan, and biglycan, and the tumor-suppressive roles of decorin and betaglycan." (PMID 41470114, 2025). "The presence of hyaluronan and versican in the pericellular matrix has been reported to promote prostate cancer cell mobility." (PMID 39018235, 2024). "Soluble VCAN can diminish attachment of prostate cancer and melanoma cells to surfaces coated with fibronectin." (PMID 38791985, 2024). "For instance, VCAN is capable of promoting the migration of breast, gastric and prostate cancer, and its expression level can determine the prognosis of malignant tumors." (PMID 36523602, 2022). "For instance, the proteoglycan versican has been proposed as a prognostic factor in prostate cancer." (PMID 35740556, 2022). "This notion was also supported by observing that increased levels of peritumoral VCAN predicted poor prognosis in patients with early-stage prostatic cancer." (PMID 33604385, 2021). "In prostate cancer, increased concentration of stromal VCAN is an independent predictor of outcome for patients with moderately differentiated tumors." (PMID 33604385, 2021). "This suggests that ADAMTS-15 represents a potential biomarker for prostate cancer, and that augmenting versican cleavage is a possible strategy for treatment." (PMID 32354091, 2020). "VCAN and versikine can both bind hyaluronan (HA), which represents a likely tether for these molecules in prostate cancer." (PMID 32354091, 2020). "VCAN has been shown to be up-regulated in prostate cancer along with the PGs syndecan-1, perlecan, decorin, biglycan, neural/glial antigen, serglycin and lumican." (PMID 32354091, 2020). "ADAMTS-15 was found to be expressed in human prostate cancer biopsies with evidence of co-localization with VCAN and its bioactive cleavage fragment versikine." (PMID 32354091, 2020). "Together, these data indicate that ADAMTS-15 acts as a tumor suppressor in prostate cancer, likely through cleavage of VCAN to versikine, with its in vivo effects on early-stage prostate cancer cells influenced by androgens." (PMID 32354091, 2020). "Together, this suggests thqat ADAMTS-15 represents a potential biomarker for prostate cancer, and that augmenting versican cleavage is a possible strategy for treatment." (PMID 32354091, 2020). "Collectively, these data are generally consistent with ADAMTS-15 utilizing VCAN as a substrate to yield versikine in prostate cancer." (PMID 32354091, 2020).
prostate carcinoma (continued). "VCAN accumulation occurs in stromal tissue in prostate cancer, potentially mediated by androgens, and is an indicator of disease relapse in clinically localized prostate cancer." (PMID 32354091, 2020). "The V1 isoform of VCAN has been shown to promote prostate cancer cell motility, leading to decreased cell attachment to fibronectin coated substrates." (PMID 32354091, 2020). "Several proteoglycans have been found to be important in prostate cancer, including versican, decorin, biglycan, lumican, and syndecan-1, and data from a range of studies implicate proteoglycan alterations to prostate cancer cell survival and metastasis." (PMID 30893936, 2019). "In prostate cancer, decorin, lumican, and versican were strongly overexpressed, although this study relied on mRNA expression data of the core proteins; thus, conclusions about the actual PG content are difficult." (PMID 32118030, 2019). "Versican is well-known as an anti-adhesive molecule, which has been reported to reduce the attachment of prostate cancer cells and melanoma to fibronectin-coated surfaces in vitro." (PMID 26416451, 2015). "This is consistent with the correlation of versican with tumor initiation and/or progression in a variety of tumors, as well as the fact that prostate cancer cells have the ability to induce host stromal cells to accumulate versican via a paracrine mechanism." (PMID 25859560, 2015). "The most studied proteoglycans in prostate cancer include extracellular proteoglycans versican, decorin and perlecan, and cell surface proteoglycans syndecan-1 and betaglycan." (PMID 23691363, 2013). "The assembly of pericellular matrix rich in HA and versican is a prerequisite for proliferation and migration of mesenchymal cells and has recently been shown to promote the motility of prostate cancer cells." (PMID 21541039, 2011). "Although FLG and VCAN are less well explored in HER2+ BC, FLG mutations have been associated with higher tumor mutation load and immunogenicity in gastric cancer, while VCAN alterations have been linked to prostate cancer progression and docetaxel resistance." (PMID 41019979, 2025). "Furthermore, versican expression increases with the acquisition of docetaxel resistance in PC-3 cells, a chemotherapeutic agent used for prostate cancer, suggesting a role of this ECM protein in resistance to treatments." (PMID 35740556, 2022). "Notably, all seven proteins were significantly associated with progression in Prostate Cancer Transcriptome Atles (PCTA) and NPM1NPM1, UQCRH, and VCAN were further validated in The Cancer Genome Atlas (TCGA), where they were upregulated in BCR+/BCR-." (PMID 35954429, 2022). "Additionally, decreased ADAMTS-5 expression was observed in prostate cancer and coincided with the accumulation of versican." (PMID 32923459, 2020). "Collectively, this research identifies the enzymatic function of ADAMTS-15 as having a tumor suppressor role in prostate cancer, possibly in concert with androgens, and that VCAN represents a likely key substrate, highlighting potential new options for the clinic." (PMID 32354091, 2020). "This is consistent with the hypothesis that ADAMTS-15 acts to cleave VCAN to form versikine in prostate cancer." (PMID 32354091, 2020). "Through versican silencing, chemoresistance could be ameliorated, indicating that versican could be a potential therapeutic target in prostate cancer." (PMID 32825245, 2020). "The pro-tumorigenic role of VCAN/HAPLN1 complex has been tested in several other tumor types, such as malignant pleural mesothelioma and breast and prostate cancers and increased tumor-specific VCAN expression levels have been reported in ACC and several other tumor types." (PMID 25587024, 2014).
prostate carcinoma (continued). "Similar to our results a higher expression of versican in the fibromuscular stroma was reported in prostate cancer tissue and in the stroma of nodules in benign prostatic hyperplasia but not in prostate epithelial cells when compared with healthy prostate samples." (PMID 23024773, 2012). "Accumulation of VCAN in peritumoural stroma was associated with the prognosis of node-negative breast cancer, early stage prostate cancer, NSCLC, oral squamous cell carcinoma, testicular germ cell tumours, cervical cancer, endometrial cancer, and epithelial ovarian cancer." (PMID 38791985, 2024). "Notably, versican is overexpressed and accumulates in the peritumoral stroma of prostate cancer." (PMID 35740556, 2022). "Thus targeting versican is a potential therapeutic strategy in docetaxel-resistant prostate cancer." (PMID 25859560, 2015). "Furthermore, it was demonstrated that breast and prostate cancer cells could increase versican production by stromal cells." (PMID 21541039, 2011). "In human prostate cancer, it has been observed that ADAMTS-15 was expressed in biopsies, with evidence of co-localization with VCAN and its bioactive cleavage fragment, versikine, suggesting a tumor suppressor role for ADAMTS-15 in prostate cancer." (PMID 39682243, 2024). "It was shown that versican is overexpressed in benign prostate hyperplasia (BPH) and prostate cancer, where it is accumulated in the stromal compartment and potentially contributes to disease pathology." (PMID 23691363, 2013). "Using the human prostate cancer cell lines LNCaP, PC-3, and DU145, it has been shown that the formation of a versican-rich pericellular matrix enhanced prostate cancer cell motility and could contribute to the development of locally invasive disease." (PMID 35740556, 2022). "Of those that can cleave VCAN, ADAMTS-1 and -15 are the most highly expressed in prostate cancer cell lines, with ADAMTS-1 demonstrated to possess tumor suppressor activity in prostate cancer, and ADAMTS-15 expression shown to be androgen-dependent." (PMID 32354091, 2020). "LNCaP represent a less malignant stage of prostate cancer than PC-3 cells, with reduced levels of both proliferation and migration as well as lower VCAN expression (data not shown), which might explain why tumor-suppressor functions for ADAMTS-15 were less readily observed in this cell line." (PMID 32354091, 2020).
gastric cancer (30 papers, 2015 to 2025). A primary or metastatic malignant neoplasm involving the stomach. "High VCAN expression was reported to be associated with poor prognosis in gastric cancer (GC) patients." (PMID 38791985, 2024). "In gastric cancer, high expression of VCAN has been associated with increased infiltration of fibroblasts, significant enrichment of stromal-associated signaling pathways, and poor prognosis." (PMID 38980810, 2024). "Association between the protein expression of THBS2 and VCAN and clinicopathologic parameters in 78 patients with gastric cancer." (PMID 36842141, 2023). "Our study found that VCAN protein was up-regulated in gastric cancer compared to that in gastritis and positively associated with tumor invasion depth and HER2 protein expression." (PMID 36842141, 2023). "As with our results, it has been documented that VCAN made an impact on the tumor mutation burden and tumor microenvironment of gastric cancer and VCAN lower expression indicated better prognosis and lower grade in GC." (PMID 36203562, 2022). "As with gastric cancer, versican expression was associated with the accumulation of T reg cells, which further contributes to mesothelioma progression by hampering the anti-tumor immune responses." (PMID 33466303, 2021). "Using gene expression profiling and IHC of tissue microarrays, it was demonstrated that versican was associated with the clinicopathological characteristics of gastric cancer and that it could be used as an independent adverse prognostic index for patients with non-metastatic gastric cancer." (PMID 37259101, 2023). "In the HPA database, the protein expression of the four model genes EDNRA, SPARC, THBSI, and VCAN was higher in gastric cancer tissues compared with normal tissues." (PMID 39040110, 2024). "Targeting VCAN holds promise for enhancing the outcomes of current clinical treatments for gastric cancer." (PMID 38791985, 2024). "In gastric cancer, VCAN is overexpressed and can predict the response to adjuvant chemotherapy, adjuvant radiotherapy and immunotherapy." (PMID 39132501, 2024). "Positive expression of VCAN protein was found in 91.03% (71/78) gastric cancer tissues and 4.55% (1/22) gastritis tissues." (PMID 36842141, 2023). "IHC was used to explore the protein expression of THBS2 and VCAN in the gastric cancer and gastritis." (PMID 36842141, 2023). "Our study found that compared with gastritis patients, THBS2 and VCAN were up-regulated in gastric cancer patients, and these individuals had a shorter survival time." (PMID 36842141, 2023). "The protein expression of THBS2 and VCAN in gastric cancer was significantly higher than that in gastritis." (PMID 36842141, 2023). "Because the bulk RNA-seq analysis revealed the high correlation between VCAN and CAFs infiltration in gastric cancer, we focused on the expression of VCAN in fibroblasts." (PMID 36203562, 2022). "Here, we assessed the impact of VCAN expression on prognosis and the response to adjuvant therapy and immunotherapy in patients with gastric cancer (GC)." (PMID 36203562, 2022). "In summary, overexpression of VCAN was often accompanied by the increase in CAFs infiltration in tumor microenvironment, which was detrimental to the prognosis of patients with gastric cancer." (PMID 36203562, 2022). "We used the KIM cohort (patients with advanced gastric cancer were treated by PD-1 inhibitor) to analyze the relationship between VCAN expression and immunotherapy responses for GC." (PMID 36203562, 2022). "In line with our result, it was reported that gastric cancer patients with high VCAN expression had worse prognoses than those with low VCAN expression and VCAN was an independent risk factor for OS." (PMID 35568824, 2022). "To further explore the landscape of VCAN expression in gastric cancer, we assessed the mRNA expression level of STAD samples from the TCGA database (TCGA cohort, n = 388) and GSE66229 dataset (ACRG cohort, n = 300)." (PMID 36203562, 2022).